TMEM176A (transmembrane protein 176A)
Synonyms: HCA112; MS4B1; GS188
Tractability: Antibody: UniProt predicts a signal peptide or a membrane-spanning region. PROTAC: its protein half-life has been measured.
Gene: Protein-coding gene on chromosome 7 (150,799,598 to 150,805,122, forward strand). Ensembl gene ENSG00000002933.
Subcellular location: Membrane
Subcellular location (Human Protein Atlas): Mitochondria
Gene Ontology:
Molecular function: protein binding
Biological process: negative regulation of dendritic cell differentiation
Cellular component: membrane
Genetic constraint (gnomAD): Loss-of-function variants: 20 observed, 26.7 expected, observed/expected ratio (o/e) 0.75, 90% interval 0.53 to 1.09. The upper end of that interval is the gene's LOEUF score, 1.09, which puts it in group 4 of 6, group 1 being the genes least tolerant of losing a copy. Missense variants: 251 observed, 285.36 expected, observed/expected ratio (o/e) 0.88, 90% interval 0.79 to 0.98. Synonymous variants: 125 observed, 118.2 expected, observed/expected ratio (o/e) 1.06, 90% interval 0.91 to 1.23.
Homologues: Orthologues: chimpanzee TMEM176A (93% identical), guinea pig TMEM176A (60% identical), pig TMEM176A (57% identical), rat Tmem176a (56% identical), mouse Tmem176a (55% identical), dog TMEM176A (54% identical). Paralogues in human: TMEM176B (32% identical).
Diseases named in the same sentence as TMEM176A in open-access papers:
TMEM176A is named in the same sentence as 37 diseases in open-access papers, as found by Europe PMC text mining. Sharing a sentence is not in itself a finding about the gene and the disease. The quoted sentences say what the papers report.
colorectal cancer (6 papers, 2017 to 2025). A primary or metastatic malignant neoplasm that affects the colon or rectum. "Briefly, hypermethylation of TMEM176A is associated with metastasis and reduced overall survival in colorectal cancer while UNC5D is a novel putative metastatic suppressor gene shown to be commonly hypermethylated in prostate cancer." (PMID 34922619, 2021). "Loss of/reduced expression of TMEM176A was found in colorectal cancer by our transcriptome study (Epigenetics2017, in press)." (PMID 29050260, 2017). "In our recent study, loss of TMEM176A expression was shown to be a frequent event in human colorectal cancer by transcriptome analysis [Epigenetics 2017, in press]." (PMID 29050260, 2017). "Knockdown of the TMEM176A gene has been shown to inhibit the proliferation, migration, and invasion of colorectal cancer cells, indicating a possible role for TMEM176A in the invasion and metastasis of colorectal cancer." (PMID 39717774, 2024). "These two studies together presented TMEM176A as tumor suppressor of esophageal squamous cell carcinoma and colorectal cancer." (PMID 30574087, 2018). "In colorectal cancer as well as in esophageal squamous cell carcinoma, TMEM176A overexpression inhibited cell migration and invasion, induced apoptosis and inhibited cell growth both in vitro and in vivo." (PMID 30574087, 2018). "However, TMEM176A negatively regulated cell invasion through reducing the expression of MMP-2/9 in different types of cancer such as glioma, esophageal, liver, and colorectal cancers." (PMID 37367036, 2023).
hepatocellular carcinoma (6 papers, 2012 to 2024). A malignant tumor that arises from hepatocytes. "Human TMEM176A was initially discovered as a candidate in a screen looking for tumor-associated antigens in human hepatocellular carcinoma (HCC)." (PMID 36814908, 2023). "In human hepatocellular carcinoma, epigenetic silencing of TMEM176A promotes ERK signalling." (PMID 36302939, 2022). "The role of TMEM176A in human hepatocellular carcinoma (HCC) is unknown." (PMID 30400968, 2018). "Human transmembrane protein 176A (TMEM176A) was first identified by screening tumor related antigens in hepatocellular carcinoma (HCC)." (PMID 29050260, 2017). "In hepatocellular carcinoma (HCC) cells, SAR1A interacts with TMEM176A to inhibit ERK signaling, thereby suppressing HCC cell growth." (PMID 39595043, 2024).
breast carcinoma (4 papers, 2015 to 2024). "Abnormal DNA methylation of CpG islands in human TMEM176A and TMEM176B is associated with breast cancer development." (PMID 39717774, 2024). "We evaluated breast cancer single-cell RNA-seq data (n = 6 TNBC) and found that the SDR42E1 expression in our diagnostic biopsy samples is likely of epithelial cell origin while the TMEM176A/B expression is likely of stromal origin." (PMID 34922619, 2021). "TMEM176A and TMEM176B, two transmembrane proteins that were recently found to be elevated in breast cancer and other human malignancies were significantly elevated in the CD24+ cells." (PMID 26040280, 2015). "TMEM176A and TMEM176B are closely related members of the MS4 transmembrane protein family, and have previously been found to physically interact, and their mRNA expression is highly correlated in the TCGA (R2 = 0.88) and METABRIC (R2 = 0.78) human breast cancer datasets." (PMID 34943938, 2021). "Additionally, the expression levels of TMEM176A and TMEM176B differ significantly between cancerous and normal tissues in breast cancer, lymphoma, skin cancer, and liver cancer, suggesting their potential as diagnostic markers for tumors." (PMID 39717774, 2024).
esophageal cancer (4 papers, 2017 to 2024). A primary or metastatic malignant neoplasm involving the esophagus. "Methylation of 18 CpG sites in the promoter region was associated to loss off/reduced expression of TMEM176A in 184 cases of esophageal cancers (Pearson: R= -0.3683098, p= 0.000, Spearman: rho= -0.3782967, p= 0.000)." (PMID 29050260, 2017). "TMEM176A is located in human chromosome 7q36.1, a region which shows frequent loss of heterozygosity in human esophageal cancer." (PMID 29050260, 2017). "In our previous studies, the TMEM176A promoter was frequently methylated in human colorectal and esophageal cancers and served as a tumor suppressor in these cancers." (PMID 30400968, 2018). "In our previous study, TMEM176A was found to be frequently methylated in human colorectal and esophageal cancers." (PMID 30400968, 2018). "In this study, we investigated the epigenetic regulation and function of TMEM176A in esophageal cancer." (PMID 29050260, 2017). "In this study, we found that the expression of TMEM176A is frequently lost in esophageal cancer cells, and the expression of TMEM176A is regulated by promoter region methylation." (PMID 29050260, 2017). "TMEM176A staining was observed mainly in the cytoplasm and cell membrane of the esophageal cancer cells." (PMID 29050260, 2017). "The tumor weight was significantly different (P<0.05), suggesting that TMEM176A suppresses esophageal cancer cell tumor growth in vivo." (PMID 29050260, 2017). "The levels of TMEM176A expression were significantly lower in esophageal cancer tissue samples compared to matched adjacent tissue samples." (PMID 29050260, 2017). "To evaluate the effects of TMEM176A on clonogenicity in esophageal cancer, we performed colony formation assays." (PMID 29050260, 2017). "TMEM176A was methylated in 66.7% (178/267) of primary esophageal cancer samples, and promoter region methylation was significantly associated with tumor differentiation (p<0.001) and loss off/reduced expression of TMEM176A (p<0.05)." (PMID 29050260, 2017). "The expression of TMEM176A was detected by semi-quantitative RT-PCR in human esophageal cancer cell lines." (PMID 29050260, 2017). "Further experiments indicated that TMEM176A induces apoptosis and inhibits esophageal cancer cell proliferation, invasion and migration." (PMID 29050260, 2017). "TMEM176A suppressed esophageal cancer cell growth both in vitro and in vivo." (PMID 29050260, 2017). "TMEM176A suppresses esophageal cancer cell tumor growth in xenograft mice." (PMID 29050260, 2017). "TMEM176A inhibited cell invasion and migration, and induced apoptosis in esophageal cancer cells." (PMID 29050260, 2017). "TMEM176A was methylated in 66.7% human primary esophageal cancer." (PMID 29050260, 2017). "Thus, TMEM176A methylation may serve as an esophageal cancer detection marker." (PMID 29050260, 2017). "TMEM176A negatively regulates the invasive function of cells and it reduces the expression of MMP2, MMP9 in different types of tumors, such as glioma, colorectal, liver, and esophageal cancers." (PMID 38850316, 2024). "TMEM176A was methylated in 66.7% (178/267) of esophageal cancer samples and no methylation (0/27) was found in non-cancerous esophageal mucosa." (PMID 29050260, 2017).
glioblastoma (4 papers, 2022 to 2025). The most malignant astrocytic tumor (WHO grade IV). "TMEM176A in glioblastoma can inhibit Bcl2 expression and cause apoptosis." (PMID 36302939, 2022). "Both gene and protein expressions of TMEM176A are raised in glioblastoma, and it promotes the cell cycle via the ERK1/2 signalling pathway." (PMID 39001509, 2024).
lung carcinoma (4 papers, 2023 to 2024). "The expression of these proteins is elevated in lymphoma, and notably, TMEM176A shows a significant increase in expression in lung cancer." (PMID 39001509, 2024). "In human lung cancer, it was reported that TMEM176A potently inhibited the growth of lung cancer cells both in vitro and in vivo by inhibiting ERK signaling." (PMID 36814908, 2023).
glioma (3 papers, 2022 to 2024). A benign or malignant brain and spinal cord tumor that arises from glial cells (astrocytes, oligodendrocytes, ependymal cells). "In conclusion, MS4A4A, MS4A4E, MS4A6A, MS4A7, TMEM176A, and TMEM176B may act as potential diagnostic or prognostic biomarkers in glioma and play a role in forming the immune microenvironment in gliomas." (PMID 35734424, 2022). "In TCGA data, the expression level of MS4A4A, MS4A4E, MS4A6A, MS4A7, TMEM176A, and TMEM176B in IDH wild-type glioma was elevated." (PMID 35734424, 2022). "We found that TMEM176A expression in tumor cells and TMEM176B expression in tumor cells, age, WHO grade, and IDH status were independent prognostic factors in glioma." (PMID 35734424, 2022). "Using bioinformatics analysis methods based on the data from public databases, we found that the expression of MS4A4A, MS4A4E, MS4A6A, MS4A7, TMEM176A, and TMEM176B was significantly overexpressed in glioma tissues compared with that of normal tissues." (PMID 35734424, 2022). "The Cox proportional hazards regression model indicates TMEM176A and TMEM176B expressions in tumor cells are independent prognostic indicators of glioma." (PMID 35734424, 2022). "In brief, these findings suggest that TMEM176A and TMEM176B are prognosis-related biomarkers in glioma." (PMID 35734424, 2022). "Therefore, these preliminary results indicate that MS4A4A, MS4A4E, MS4A6A, MS4A7, TMEM176A, and TMEM176B are potential prognostic factors for glioma." (PMID 35734424, 2022). "Moreover, the C-index values for the prediction model of TMEM176A and TMEM176B were 0.832 and 0.833, indicating a moderate predictive accuracy for OS in glioma." (PMID 35734424, 2022). "In TCGA data, the expression level of MS4A4A, MS4A4E, MS4A6A, MS4A7, TMEM176A, and TMEM176B in 1p/19q non-codel glioma was elevated." (PMID 35734424, 2022).
liver cancer (3 papers, 2021 to 2023). An epithelial or non-epithelial malignant neoplasm that arises from the liver. "An increasing body of evidence suggests that TMEM176A can inhibit tumor cell growth and migration by constraining extracellular signal-regulated kinase (ERK) signal transduction in lung, pancreatic and liver cancer." (PMID 37064154, 2023). "The TMEM176A gene is present in BLCA and is highly expressed in liver cancer." (PMID 36016607, 2022).
pancreatic cancer (2 papers, 2023 to 2024). "Nevertheless, TMEM176A has been identified as a tumour suppressor in pancreatic cancer, primarily regulated through the ERK signalling pathway." (PMID 39001509, 2024). "TMEM176A suppresses the progression of pancreatic cancer cells by inhibiting ERK signaling." (PMID 37367036, 2023).
schizophrenia (2 papers, 2013 to 2023). A major psychotic disorder characterized by abnormalities in the perception or expression of reality. "The transmembrane protein TMEM176A gene isassociated with schizophrenia." (PMID 37867610, 2023). "Also, we observed three SZUP genes (BAZ1A, TMEM176A, and FTL) in this module in the control network, but not in the schizophrenia network." (PMID 24070017, 2013).
spinal cord injury (2 papers, 2020 to 2024). Penetrating and non-penetrating injuries to the spinal cord resulting from traumatic external forces (e.g., WOUNDS, GUNSHOT; WHIPLASH INJURIES; etc.). "It has been suggested that TMEM176A and TMEM176B inhibit the maturation and activation of dendritic cells in chronic spinal cord injury and that TMEM176B impairs IL-1β secretion and reduces CD8+ T cell-dependent antitumor immunity." (PMID 39684780, 2024). "TMEM176A and TMEM176B, which were suggested to inhibit DC maturation in chronic spinal cord injury, were expressed in three subtypes of monocytes." (PMID 33603736, 2020).
Alzheimer disease (1 paper, 2016). A progressive, neurodegenerative disease characterized by loss of function and death of nerve cells in several areas of the brain leading to loss of cognitive function such as memory and language. "Upregulation of TMEM176A/B in Alzheimer’s disease was attributed to lower/less effective functioning of macrophages in lipid clearance." (PMID 27374485, 2016).
Autoimmunity (1 paper, 2023). The occurrence of an immune reaction against the organism's own cells or tissues. "Intriguingly, upregulated TMEM176A expression has been demonstrated to prevent dendritic cell (DC) maturation and inhibit DC activity in the general population when DCs have been shown to mediate recovery from central nervous system damage and/or protective autoimmunity." (PMID 37064154, 2023).
COVID-19 (1 paper, 2023). A disease caused by infection with severe acute respiratory syndrome coronavirus 2. "For instance, IL1B, NFKB1, NLRP3, PYCARD, and CASP1 are listed in the COVID-19 Disease Map, while there are molecules absent from it, including CCL3, 3L1, 4L2, CXCL1, 2, 3, 5, 16, TNFAIP6, C15orf48, TMEM176A/B, NFE2, PADI4, RAB20, ETS2, PHLDA2, FOLR3, and HP." (PMID 37719701, 2023).
gastric cancer (1 paper, 2025). A primary or metastatic malignant neoplasm involving the stomach. "Spatial transcriptomics indicates that TMEM176A expression is predominantly localized to fibroblasts, whereas conventional gastric cancer cell lines are epithelial and lack a stromal component, limiting functional assessment in vitro." (PMID 41228276, 2025). "Although research on TMEM176A in gastric cancer is limited, our single-cell and spatial transcriptomic analyses localize TMEM176A expression predominantly to fibroblasts and myeloid cells." (PMID 41228276, 2025). "HPA immunohistochemistry confirmed higher TMEM176A and SRI protein levels in gastric cancer versus adjacent mucosa." (PMID 41228276, 2025).
lymphoid neoplasm (1 paper, 2025). A neoplasm composed of a lymphocytic cell population which is usually malignant (clonal) by molecular genetic and/or immunophenotypic analysis. "In tumors, TMEM176A is overexpressed across diverse malignancies, including breast, liver, and skin cancers as well as lymphoid neoplasms." (PMID 41228276, 2025).
migraine (1 paper, 2025). "Five genes were replicated both in the migraine dataset and in IBD-Character: TMEM176A, TMEM176B, PI3, HIST1H2BD, and HIST1H2AD." (PMID 41010012, 2025).
osteoarthritis (1 paper, 2023). A noninflammatory degenerative joint disease occurring chiefly in older persons, characterized by degeneration of the articular cartilage, hypertrophy of bone at the margins and changes in the synovial membrane. "We performed in-depth analyses to disentangle the role of adiposity on comorbidity and find evidence that TCF7L2 and TMEM176A exert an effect on type 2 diabetes and osteoarthritis through an alternative biological path." (PMID 37433298, 2023). "Variants in TMEM176A, also a high-confidence effector gene for the investigated comorbidity, have not been previously identified as implicated in either osteoarthritis or type 2 diabetes in the previous recent GWAS for the individual diseases." (PMID 37433298, 2023). "Similar to the TCF7L2 locus case, our results suggest that the mechanism through which TMEM176A exerts an effect on osteoarthritis and type 2 diabetes may have contrary directions." (PMID 37433298, 2023).
type 2 diabetes (1 paper, 2023). "While TMEM176A is more highly expressed in pancreatic islets of diabetic individuals than in healthy pancreatic islets, an increase of its expression in the same tissue has a causal effect on increased risk of type 2 diabetes." (PMID 37433298, 2023).